BRCA2 (BRCA2 DNA repair associated)
Diseases named in the same sentence as BRCA2 in open-access papers (continued):
Sharing a sentence is not in itself a finding about the gene and the disease.
Fibroadenoma (5 papers, 2009 to 2025). A benign tumor of the breast characterized by the presence of stromal and epithelial elements. "Among the markers associated with cell repair, BRCA2 displayed significantly higher expression in fibroadenoma samples from rats exposed to the diet." (PMID 40806434, 2025). "KRT5, TGF-β, PAI-1, HIF-1α, TIMP1, MMP2, TWIST1, VEGFα, and BRCA2 were all significantly upregulated in fibroadenomas." (PMID 40806434, 2025). "Although malignant transformation in a fibroadenoma is rare, high suspicion index in middle aged women with fibroadenoma and associated risk factors like strong family history and/or BRCA-1, BRCA-2 mutation is recommended." (PMID 20072677, 2009). "We have identified the methylation of five cancer-related CpG islands in the giant fibroadenoma tissue: ESR1, MGMT, WT-1, BRCA2 and CD44." (PMID 22011321, 2011). "Fibroadenoma (FA) was diagnosed in 235 participants (134 BRCA1 carriers and 101 BRCA2 carriers)." (PMID 40694193, 2025). "However, unlike BRCA2, 29.5% of BRCA1 mutations display posterior echo enhancement, usually in benign breast lesions, such as fibroadenomas or cysts." (PMID 35402620, 2022).
head and neck cancer (5 papers, 2015 to 2023). A primary or metastatic malignant neoplasm affecting the head and neck. "Others showed that BRCA1 or BRCA2 mutation does not increase head and neck cancer incidence." (PMID 34577828, 2021).
intrahepatic cholangiocarcinoma (5 papers, 2021 to 2024). A carcinoma that arises from the intrahepatic bile duct epithelium in any site of the intrahepatic biliary tree. "BRCA2, CDKN2A, and FGFR2 mutations were most frequently identified in case of intrahepatic cholangiocarcinoma." (PMID 34316332, 2021).
invasive carcinoma (5 papers, 2010 to 2025). A carcinoma that is not confined to the epithelium, and has spread to the surrounding stroma. "We used immunohistochemistry to examine the expression of the hypoxia markers HIF-1α, CAIX and Glut-1 in DCIS and available invasive carcinoma lesions of 32 BRCA1, 16 BRCA2 and 77 non-BRCA mutation-related cases." (PMID 23409121, 2013).
metastasis (5 papers, 2015 to 2024). The spread or migration of cancer cells from one part of the body (where they first appeared) to another. "The BRCA2 mutation was associated with liver metastasis (p = 0.0162)." (PMID 34205170, 2021). "In a recent article, the overall rates of CNS metastasis were remarkably higher in patients with both BRCA1 and BRCA2 mutations than in noncarriers (BRCA1: 53% and BRCA2: 50% vs. noncarriers: 25%, respectively)." (PMID 33802424, 2021). "Statistically significant relationships were present between KRAS exon 2 and mucinous morphology, PIK3CA and absence of perineural invasion, BRAF and tumor differentiation/localization, MutS homolog 3 (MSH3) and tumor diameter, and BRCA2 and absence of lymph node metastasis." (PMID 37737217, 2023).
microcephaly (5 papers, 2012 to 2023). A congenital or acquired developmental disorder in which the circumference of the head is smaller than normal for the person's age and sex. "On the other hand, biallelic hypomorphic mutations in BRCA2 have been associated to hypersensitivity to DNA damage and FA leading to the manifestation of microcephaly in affected patients." (PMID 37881689, 2023). "Analyzed at P0, Brca2 deletion by Emx1Cre (Emx1Cre/+;Brca2fl/fl, Brca2 cKO-E) led to significant microcephaly, callosal agenesis, and hippocampal hypoplasia remarkably similar to Ino80 cKO-E." (PMID 32737294, 2020). "The severity of the microcephaly is distinct from BRCA2 homozygous deletion mice, where a milder microcephaly phenotype was observed." (PMID 22292003, 2012). "We observed one single m6A site near the stop codon in 7 microcephaly-related E-SMRs, including Brca2, Cep152, Ddx11, Nde1, Kif14, Stil and Cdk5rap2, 3 polymicrogyria-related E-SMRs (Eomes/Tbr2, Pax6 and Foxp2), and 3 megalencephaly-related E-SMRs (Gli3, Ccnd2 and Kif7)." (PMID 32992647, 2020). "In mice, inactivation of Brca2 (Brca2LoxP/LoxP; Nestin-cre) led to increased levels of yH2AX foci followed by apoptosis in both NPCs and early post-mitotic neurons, that culminates in defective neural development leading to microcephaly due to genotoxic stress." (PMID 37881689, 2023).
ovarian adenocarcinoma (5 papers, 2016 to 2023). An adenocarcinoma that arises from the ovary. "In a separate study, a nonsense mutation in BRCA2 became inactivated by a TAG > TAT SNV in a cisplatin-treated ovarian adenocarcinoma following a cisplatin-resistant relapse." (PMID 27161042, 2016). "To determine if the LivePAR nuclear enrichment assay could identify decreased PARylation associated with cisplatin-mediated reversion and reactivation of BRCA2, we compared the BRCA2 deficient ovarian adenocarcinoma cell line PEO1 with its cisplatin-resistant BRCA2-revertant clone C4-2." (PMID 35954352, 2022).
pancreatic acinar cell carcinoma (5 papers, 2015 to 2025). An adenocarcinoma arising from the pancreas. "These cases highlight the need for further study on utilizing PARP inhibitors for pancreatic acinar cell carcinoma patients with germline BRCA-2 mutations." (PMID 39410042, 2024).
Pancreatic cysts (5 papers, 2016 to 2024). A cyst of the pancreas that possess a lining of mucous epithelium. "Six of the 27 mutation carriers (22%) had pancreatic cysts of unknown type detected, including 1 ATM carrier, 3 BRCA2 carriers, and 2 CDKN2A carriers." (PMID 32601617, 2019).
pancreatic neuroendocrine tumor (5 papers, 2019 to 2025). Pancreatic endocrine tumor, also known as pancreatic neuroendocrine tumor (PNET), describes a group of endocrine tumors originating in the pancreas that are usually indolent and benign, but may have the potential to be malignant. "Furthermore, MUTYH/CHEK2, BRCA2, CDKN2A, and TIMP3 have also been associated with pancreatic neuroendocrine tumors." (PMID 35163032, 2022).
prostate intraepithelial neoplasia (5 papers, 2010 to 2022). A neoplastic proliferation of the epithelial cells that line the acini and the ducts of the prostate gland. "Using a genetically engineered mouse model, it was found that deletion of Brca2 in prostate epithelia resulted in focal hyperplasia and low-grade prostate intraepithelial neoplasia (PIN) in animals over 12 months old." (PMID 31197228, 2020). "We show that deletion of Brca2 specifically in prostate epithelia results in focal hyperplasia and low-grade prostate intraepithelial neoplasia (PIN) in animals over 12 months of age." (PMID 20585617, 2010).
rhabdomyosarcoma (5 papers, 2017 to 2025). A rare aggressive malignant mesenchymal neoplasm arising from skeletal muscle. "BRCA2 gene, retinoblastoma gene and the alveolar rhabdomyosarcoma gene FOXO1A to mention a few, have been identified on chromosome 13." (PMID 36289492, 2022).
serous ovarian tumors (5 papers, 2019 to 2024). "rs11571833 lies in the BRCA2 coding region and produces a truncated form of the protein and has been shown to be associated with both risk of TN disease and risk of serous ovarian tumors, both of which tend to be high-grade." (PMID 34983606, 2022). "However, similar to studies in TNBC, we found that average AR expression was higher in BRCA1 and BRCA2-mutated high-grade serous ovarian tumors compared to non-mutated BRCA tumors." (PMID 34926721, 2019).
xeroderma pigmentosum (5 papers, 2019 to 2024). Xeroderma pigmentosum (XP) is a rare genodermatosis characterized by extreme sensitivity to ultraviolet (UV)-induced changes in the skin and eyes, and multiple skin cancers. "In addition, inherited conditions such as xeroderma pigmentosum (XP), congenital melanocytic nevi, familial atypical multiple moles and melanoma (FAMMM) syndrome, and BRCA2 mutation all provide evidence for a genetic predisposition to the development of melanoma." (PMID 33339193, 2020). "BRCA2 and ERCC2 are also linked with classical cancer predisposition syndromes, hereditary breast and ovarian cancer (HBOC) and xeroderma pigmentosum (XP), respectively." (PMID 30871259, 2019).
acinar cell carcinoma (4 papers, 2015 to 2026). "Two patients exhibited germline BRCA2 mutations: one with adenocarcinoma and the other with acinar cell carcinoma." (PMID 41668632, 2026). "Acinar carcinomas and neuroendocrine carcinomas only developed in mice with homozygous Brca2 mutation." (PMID 35163129, 2022). "Recurrent premature termination mutations of BRCA2 with loss of the wild-type allele were identified in 3 of the 7 acinar cell carcinomas analyzed by exome and target sequencing." (PMID 25743105, 2015). "Consistent with our data, associations between acinar cell carcinomas and genetic aberrations of BRCA2 have often been reported." (PMID 25743105, 2015). "In conclusion, acinar cell carcinomas show a distinct mutation pattern and often harbor somatic or germline mutations of BRCA2 and FAT genes." (PMID 25743105, 2015). "We identified recurrent mutations of BRCA2 in 3 of 7 acinar cell carcinomas in the sequencing analyses." (PMID 25743105, 2015). "Simultaneous loss of both Brca2 alleles may trigger carcinogenesis of variant histopathology, such as acinar cell carcinoma." (PMID 35163129, 2022). "Acinar cell carcinoma may commonly harbor somatic or germline loss-of-function mutations of BRCA2 and FAT genes." (PMID 25743105, 2015). "Moreover, 5 of the 11 acinar cell carcinomas examined by immunohistochemistry revealed loss of BRCA2 expression." (PMID 25743105, 2015). "We identified recurrent mutations of BRCA2 and FAT genes, along with an unexpected contribution of germline variations, in acinar cell carcinomas." (PMID 25743105, 2015). "Then, we performed target sequencing analyses for the entire coding regions of BRCA1, BRCA2, FAT1, and FAT4 via a semiconductor sequencer in an additional 4 cases of acinar cell carcinoma, using archival formalin-fixed and paraffin-embedded (FFPE) tissues." (PMID 25743105, 2015).
ampullary cancer (4 papers, 2016 to 2025). "A representative case report of this finding describes a patient with a metastatic ampullary cancer with BRCA2 germline mutation and TMB of 11 mut/Mb, who actually had a marked response to chemotherapy." (PMID 40575172, 2025). "One more patient carrying the BRCA2 c.156_157insAlu mutation was identified in this series, giving a total of two (12.5%) positive samples in the 16 cases of ampullary cancer analyzed for founder mutations." (PMID 27532258, 2016). "BRCA2 mutations were observed with a frequency of 14.3% in ampulla of Vater carcinomas." (PMID 27532258, 2016). "Furthermore, we identified for the first time a high frequency of germline BRCA2 mutations in ampullary cancers." (PMID 27532258, 2016). "Analysis of the patient with ampullary carcinoma showed BRCA2 and postmeiotic segregation increased 2 (PMS2) alterations in the primary tumor but no mutations in cfDNA." (PMID 37108676, 2023). "In ampullary cancers, we here show for the first time a frequency of 14.3% BRCA1/BRCA2 mutations after a combination of direct founder mutation testing and full gene analysis in archival tissue with NGS." (PMID 27532258, 2016).
benign breast disease (4 papers, 2011 to 2020). "Relatedly, CCF08133, a 71-year old male with BRCA2 c.4876_4877delAA, p.N1626fs*12 truncating variant, had benign breast disease, not otherwise specified." (PMID 29684080, 2018).
colorectal tumor (4 papers, 2004 to 2022). "To the best of our knowledge, we are the first to characterize the BRCA2 T1346I variant, within the context of the full-length protein, found somatically mutated in a colorectal tumor specimen." (PMID 36098506, 2022). "In addition, we identified a BRCA2 T1346I variant as a somatic mutation from whole exome sequencing (WES) of a colorectal tumor specimen from the Yale Cancer Center." (PMID 36098506, 2022).
coronary artery disease (4 papers, 2017 to 2025). "The present study was to detect the association of single nucleotide polymorphism (SNP) in the breast susceptibility gene 2 (BRCA2) and the risk of coronary artery disease (CAD) and ischemic stroke (IS)." (PMID 28982360, 2017). "BRCA2 SNP rs9534275 not only is associated with LDL and total cholesterol but also with increased risk of coronary artery disease and ischemic stroke along with increased risk for benign breast cancer (NCBI: ClinVar)." (PMID 32638521, 2020).
esophageal squamous cell carcinoma (4 papers, 2021 to 2025). Esophageal squamous cell carcinoma (ESCC) is a type of esophageal carcinoma (EC) that can affect any part of the esophagus, but is usually located in the upper or middle third. "An extrapolation to therapeutic classes is not yet guideline-anchored for the specific mutation-tumor combination (eg, PARP inhibitors in BRCA2-mutant esophageal SCC, or RAF inhibitors in GBM)." (PMID 40973166, 2025). "Only a few studies have revealed the association of loss of function mutation in BRCA2 with familial esophageal squamous cell carcinomas." (PMID 39421182, 2024).
heart failure (4 papers, 2017 to 2026). Inability of the heart to pump blood at an adequate rate to meet tissue metabolic requirements. "Loss of breast cancer susceptibility gene 2 (BRCA2) function was found to exacerbate doxorubicin-mediated cardiomyocyte apoptosis and promote heart failure progression." (PMID 41625597, 2026). "Of the 7.7% of BRCA1 and BRCA2 mutation carriers who developed heart failure, 8.3% were anthracycline naïve (statistically significant at p ≤ 0.001) compared with the general population risk of 2%." (PMID 28157161, 2017). "One prior exploratory study of 401 patients, including 232 BRCA1 and 159 BRCA2 mutation carriers, showed an increased risk of heart failure based on self-reported symptoms elicited on an anonymous survey, relative to historical controls drawn from the general population." (PMID 35242827, 2022). "Previous studies showed that some genetic alterations, including BRCA1, BRCA2, and ATM mutations, not only predispose to early-onset PCa but also correlate with increased cardiovascular risk and heart failure development." (PMID 40805117, 2025).
liposarcoma (4 papers, 2016 to 2026). A usually painless malignant tumor that arises from adipose tissue. "Partial responses were achieved in two cases: a liposarcoma patient with a BRCA2 mutation treated with PARP inhibitors (Olaparib and Talazoparib; PFS 29.5 months) and a patient with an NTRK1 fusion who received Larotrectinib (PFS 57.7 months)." (PMID 41562936, 2026). "These included a patient with liposarcoma harboring a BRCA2 mutation treated with PARP inhibitors (PFS 29.5 months) and a patient with an NTRK1 fusion treated with larotrectinib (PFS 57.7 months)." (PMID 41562936, 2026). "Signature 3, the canonical double-strand break signature linked to mutations in BRCA1 or BRCA2 or to a BRCAness phenotype, was more pronounced in cases with chromothripsis in liposarcoma." (PMID 32385320, 2020).
male infertility (4 papers, 2007 to 2021). The inability of the male to effect fertilization of an ovum after a specified period of unprotected intercourse. "Intriguingly, an association of the BRCA2 N372H variant with idiopathic male infertility, a condition possibly related to increased sensitivity to estrogens, has been recently suggested." (PMID 17767707, 2007). "Most SNP-populated genes related to male infertility include HLA-DQB1 (20 SNPs), HLA-DRB1 (15 SNPs), MTHFR (10 SNPs), BRCA2 (9 SNPs), ACE (8 SNPs), CFTR (6 SNPs), CDH1 (6 SNPs), SRD5A2 (6 SNPs), HLA-DQA1 (5 SNPs) and MMP9 (5 SNPs)." (PMID 29263816, 2016).
mismatch repair deficiency (4 papers, 2017 to 2023).
mucinous carcinoma (4 papers, 2020 to 2025). "BRCA2 mutation has been reported in some forms of mucinous carcinoma (MC) such as colorectal and gastric-type of the uterine cervix." (PMID 40225096, 2025). "We detected both previously reported (HNF1, SUFU) and unreported (BRCA2, GRIN2A) alterations associated with mucinous adenocarcinoma." (PMID 40302146, 2025).
myeloid neoplasm (4 papers, 2019 to 2025). Proliferation of myeloid cells originating from a primitive stem cell. "P/LP likely germline variants in genes that have previously been associated with adult myeloid malignancy were found in 16 patients (4.4%), including ATM, BRCA2, CHEK2, and TNFRSF13B." (PMID 40766138, 2025).
non-Hodgkin lymphoma (4 papers, 2014 to 2024). Distinct from Hodgkin lymphoma both morphologically and biologically, non-Hodgkin lymphoma (NHL) is characterized by the absence of Reed-Sternberg cells, can occur at any age, and usually presents as a localized or generalized lymphadenopathy associated with fever and weight loss. "One of these cancers (in a father) was non-Hodgkin’s lymphoma, for which there is some evidence of association with pathogenic variants in BRCA2." (PMID 39438716, 2024).
non-melanoma skin carcinoma (4 papers, 2004 to 2025). "The risk of non-melanoma skin cancer in women who carry a mutation in BRCA1 or BRCA2 is similar to that of non-carrier women." (PMID 38741145, 2024). "Among women included in the analysis, 379 (12%) of BRCA1 PV carriers, 646 (20%) of BRCA2 PV carriers and 645 (23%) of non-carriers experienced natural menopause prior to RRSO, a cancer diagnosis (apart from non-melanoma skin cancer) or interview." (PMID 40399999, 2025).
renal carcinoma (4 papers, 2021 to 2026). A carcinoma arising from the epithelium of the renal parenchyma or the renal pelvis. "For example, patients with pathogenic BRCA2 variants (such as one of our RCC cases) have an increased risk of renal cancer progression." (PMID 41341482, 2026).
Renal cyst (4 papers, 2021 to 2025). A fluid filled sac in the kidney. "It is therefore plausible that the renal cysts observed in this case are associated with BRCA2-related fibrotic processes." (PMID 40723533, 2025). "Although histologic confirmation of carcinoma was not obtained in this case, the findings suggest that BRCA2 mutations may contribute not only to the formation of renal cysts but also potentially to later neoplastic progression." (PMID 40723533, 2025).